TNF (tumor necrosis factor)
Diseases named in the same sentence as TNF in open-access papers (continued):
Sharing a sentence is not in itself a finding about the gene and the disease.
Insulin resistance (continued). "However, oleate not only did not induce cardiovascular insulin resistance but also had a protective effect against insulin resistance induced by palmitate or TNFα." (PMID 26055507, 2015). "In addition, in obese humans, a proinflammatory cytokine, TNF-α was found in plasma and served as a marker of insulin resistance." (PMID 24441717, 2014). "TNF- and ROS may activate inflammatory pathways and promote the expression of numerous genes involved in insulin resistance." (PMID 25313561, 2014). "TNF-α also promotes the incorporation of fatty acids into diacylglycerol, which may contribute to the development of TNF-α induced insulin resistance in skeletal muscle." (PMID 24563869, 2014). "Dysregulation of adipokines originating from visceral adipose tissue, such as tumor necrosis factor-α (TNF-α), interleukin-6 (IL-6), leptin, and adiponectin, has been reported to influence insulin resistance and growth hormone (GH) secretion, which are closely associated with sarcopenia." (PMID 25517117, 2014). "It has been hypothesized that activated innate and adaptive immune cells stimulate release of cytokines such as TNFα and IL-1β, which promote both systemic insulin resistance and β-cell damage." (PMID 25102180, 2014). "Moreover an agent that inhibits TNF production and another that controls insulin resistance have both been shown to reverse AD in experimental models." (PMID 25231068, 2014). "Thus, moderate hyperinsulinemia in response to insulin resistance or lowering of TNF-α levels within the aorta attenuates vascular damage, this protective effect being mediated by UCP-2 expression levels through iNOS." (PMID 25077985, 2014). "To test our hypothesis, we treated wildtype mice or β2KO mice with etanercept for two months and measured proteins involved in insulin resistance and signaling, including TNFα, SOCS3, insulin receptor (IR), and apoptotic markers." (PMID 25138272, 2014). "The reciprocal stimulation of SOCS3 and TNF-α expression suggests that positive feedback between these two factors could play an important role in mediating the development of insulin resistance and apoptotic cell death in rMC-1 cells." (PMID 25352752, 2014). "Tumor necrosis factor alpha (TNFα) contributes to adipocyte inflammation and insulin resistance." (PMID 24804087, 2014). "Additionally, we demonstrated in retinal endothelial cells that TNFα activation of SOCS3 and IRS-1Ser307 leads to decreased insulin signal transduction, which likely underlies insulin resistance." (PMID 24695399, 2014). "Also, based on a community-based cohort study, it is proposed that the prevalence of insulin resistance increases with greater levels of resistin and TNF-α and is inversely related to adiponectin levels." (PMID 24563869, 2014). "Increased TNFα can produce insulin resistance in multiple ways." (PMID 25138272, 2014). "Among these inflammatory cytokines, the evidence that insulin resistance is linked to TNF-α, but not IL-6 and IL-8, is well established." (PMID 25202741, 2014). "Moreover, ablation of Fas (CD95), a further member of the tumor necrosis factor receptor (TNFR)-superfamily, in murine adipocytes has a similar positive effect on insulin resistance during HFD as demonstrated for TNFα and IL-6." (PMID 24897026, 2014). "Furthermore, current evidence suggests that the administration of exogenous TNF-alpha to animals can induce insulin resistance, whereas its neutralization can improve insulin sensitivity." (PMID 24991532, 2014). "A possible link exist between decreased adiponectin with increased insulin resistance, while some evidence links increased TNF-α and resistin with increased insulin resistance Another study relate higher blood pressures to decreased adiponectin, increased TNF-α, and CRP concentrations." (PMID 24571954, 2014). "The adipokines IL-6 and TNF-α are related to insulin resistance." (PMID 24465964, 2014). "It has been suggested that TNF-α is a predictor of insulin resistance in human pregnancy." (PMID 25202741, 2014).
Insulin resistance (continued). "Furthermore, TNFα has been suggested to be involved in inducing insulin resistance in adipocytes, and retinal endothelial cells (REC) through activation of insulin receptor substrate 1 (IRS-1)Ser307 and stimulation of apoptosis." (PMID 25073020, 2014). "Besides the direct effects of inflammatory cytokines on lipogenesis and fibrogenesis, MCP-1, TNF-α, and IL-1β, IL-6 can induce insulin resistance." (PMID 25136608, 2014). "Since TNFα is a key player in insulin resistance, we wanted to investigate whether blockade of TNFα actions in β2KO mice could prevent these deleterious effects." (PMID 25138272, 2014). "Moreover, the treatment with pentoxifylline, a TNF-α inhibitor, reduces amino-transferase serum levels and IR, measured by homeostatic metabolic assessment-insulin resistance (HOMA-IR) in NASH patients." (PMID 24795720, 2014). "Insulin resistance was induced by tumor necrosis factor-α (TNF-α) to a FL83B mouse liver cell line." (PMID 25421245, 2014). "Excess white adipose tissue (WAT) in obese is characterized by increased macrophage infiltration and production of proinflammatory cytokines including tumor necrosis factor-α (TNF-α) and interleukine-6 (IL-6) that mediate local and systemic effects on inducing insulin resistance." (PMID 24836538, 2014). "In addition, PTX (50 mg/kg) administered to rats for 8 weeks was shown to inhibit insulin resistance and prevent TNF-alpha elevation, leukocyte infiltration and endothelial pyknosis." (PMID 24991532, 2014). "Interestingly, TNFα is a pro-inflammatory cytokine that not only promotes insulin resistance, it also induces sarcopenia." (PMID 25337938, 2014). "Finally, the Ser307 phosphorylation of IRS-1 through TNF-α induced JNK signaling results in insulin resistance." (PMID 24481061, 2014). "We found that TNF-α in the adipose tissue of HSHF rats begins to increase by the 12th week and reaches a peak by the 36th week, which may be associated with insulin resistance (IR)." (PMID 25502558, 2014). "In addition, its activation was initially shown to inhibit TNF-α-induced inflammation, insulin resistance, apoptosis, and oxidative stress." (PMID 24829560, 2014). "Additionally, TNF-α has been demonstrated to be the most significant predictor of pregnancy-induced insulin resistance and be more highly synthesized and released from the placenta compared with IL-6 or IL-8." (PMID 25202741, 2014). "Interestingly, TNF-α has long been established as an important mediator of insulin resistance and β-cell apoptosis." (PMID 24465695, 2014). "We ascertained that the pre-treatment with 10 ng/mL TNF-α for 2 hours induced insulin resistance in both vascular cells as shown by the significant decreases in the phosphorylation of Akt, p70S6K and p44/42 in cells stimulated with 10 nmol/L insulin for 10 minutes." (PMID 25077985, 2014). "In addition, it has been demonstrated that fucoxanthin improves insulin resistance and decreases blood glucose level, at least in part, through the downregulation of tumor necrosis factor-α (TNF-α) in white adipose tissue (WAT) of animals." (PMID 24473167, 2014). "Moreover, hsCRP and IL-1β and TNF-α and IL-6 positively correlated with insulin resistance (P < 0.05)." (PMID 24795503, 2014). "One study has demonstrated that conditioned medium from 3T3-L1 adipocytes stimulated with TNFα induced insulin resistance in hepatocytes, and this could be prevented by blocking TNFα-induced IL-1β production by 3T3-L1 cells." (PMID 24918199, 2014). "In addition to these classical components, MetS mice presented with insulin resistance and systemic inflammation indicated by elevated TNF-α and reduced adiponectin levels." (PMID 24490784, 2014). "The next step to determining whether TNFα is key to insulin resistance is to evaluate whether TNFα can regulate other factors involved in impaired insulin signaling." (PMID 23592917, 2013). "TNF-α is also known as adipocytokine that can induce insulin resistance." (PMID 24079935, 2013).
Insulin resistance (continued). "Some TNF-α blockers are reported to improve insulin resistance." (PMID 23843781, 2013). "As TNF-α induced insulin resistance and miR-494 expression, we tested whether miR-494 can modulate insulin action." (PMID 24349514, 2013). "It has been reported that TNF-alpha is overexpressed in the adipose and muscle tissues of obese and insulin-resistant nondiabetic subjects, overexpression that is positively correlated with insulin resistance." (PMID 23690772, 2013). "Furthermore, the reduction of TNF-α which has an important role on insulin resistance in NAFLD patients, was seen as the reason for the observed changes." (PMID 23885277, 2013). "The authors inferred that leptin reduction is a reflection of decreased fat accretion, and changes in TNF-α could be evidence of altered insulin resistance." (PMID 23691290, 2013). "No independent associations of insulin resistance with either Leptin or TNF-α were observed in this selected south Asian group in the two models adjusting for these parameters." (PMID 23671875, 2013). "TNF-α is a critical mediator in insulin resistance induction, inhibition of which by phytol could convey the improvement of insulin sensitivity along with glucose disposal." (PMID 23300941, 2013). "Several molecules have been suggested as targets of TNF-α-mediated insulin resistance." (PMID 24349514, 2013). "However in combination, ASP + MSG significantly elevated all these parameters, and doubled fasting serum leptin and TNFα, whilst promoting insulin resistance and hepatic steatosis." (PMID 23783067, 2013). "The specific mechanisms responsible for the development of hepatic steatosis with these products are unclear but are thought to be a consequence of the hepatic metabolism of fructose favoring ATP depletion, lipotoxicity, and insulin resistance combined with an enhanced TNF expression." (PMID 23576902, 2013). "TNF-α has deteriorative property on insulin resistance in vivo." (PMID 24349514, 2013). "However, more comprehensive studies are needed to fully understand the molecular mechanism whereby TNF-α induces insulin resistance." (PMID 24349514, 2013). "TNFα is a major contributor to the development of adipose tissue insulin resistance." (PMID 23690773, 2013). "3T3-L1 cells were induced to insulin resistance using TNF-α, to test whether stevioside could exert similar effects on these cells as on normal adipocytes in terms of enhancing glucose uptake." (PMID 24391675, 2013). "As TNF-α is a major mediator in the inflammatory process that is considered an inducer of insulin resistance (reviewed in 51,52), we investigated whether insulin signaling may be affected by TNF-α in C2C12 myotubes." (PMID 24349514, 2013). "Mitochondria can be a source of TNF-α-induced ROS production in cells and this may contribute to the pathogenesis of TNF-α-induced insulin resistance." (PMID 24177571, 2013). "A key mechanism by which TNF-α induces insulin resistance involved phosphorylation of IRS-1." (PMID 24455420, 2013). "Visceral adipose tissue is believed to play a pivotal role in the pathogenesis of NAFLD, since it participates in producing most adipokines, such as Tumor Necrosis Factor alpha (TNF-alpha), resistin, and adiponectin, which are involved in inducing insulin resistance and low-grade inflammation." (PMID 23530957, 2013). "Further, due to its release by various types of cell types involving both inflammatory and noninflammatory cells which then can be involved in insulin resistance pathogenesis both by autocrine or paracrine manner, TNF-α is the subject of uncertainty regarding its precise role in insulin resistance." (PMID 23762871, 2013). "The basis of this hypothesis is that TNFα was found to contribute to the induction of insulin resistance, although its exact mechanism of action is yet to be established." (PMID 24324517, 2013).
Insulin resistance (continued). "Inflammatory mediators such as TNF-α and IL-6 either alone or through synergistic effect could lead to the development of insulin resistance by blocking the signal transduction of insulin, impairing insulin sensitivity, and increasing free fatty acids." (PMID 23840093, 2013). "Therefore, stevioside was seen to be able to potentiate in the reduction of insulin resistance through reducing the inflammation in adipose tissues by regulating TNFα." (PMID 24324517, 2013). "Moreover, our previous study indicated that in cultured human HepG2 hepatocytes, TNF-α induced insulin-resistance, as assessed by their decreased capacity to accumulate glycogen in the presence of insulin." (PMID 23437347, 2013). "Both TNF-α and IL-6, two main proinflammatory cytokines released by adipose tissue, can inhibit insulin signalling, and TNF-α may have a crucial role in the development of insulin resistance in type 2 diabetes." (PMID 23590862, 2013). "It was reported that NF-κB results in insulin resistance by activating proinflammatory cytokines like TNF-α, IL-6, IL-1β, and resistin, which consequently activates the c-Jun N-terminal kinase (JNK) and NF-κB pathways to create a vicious cycle that exacerbates tissue damage." (PMID 24348717, 2013). "The fact that PPARγ facilitates the maintenance of normal insulin sensitivity leads to the conclusion that its inhibition by TNFα could possibly account for TNFα-induced insulin resistance." (PMID 24324517, 2013). "TNF-α inhibited adipogenesis, and the inability for adipogenesis may promote adipocyte hypertrophy, contributing to insulin resistance." (PMID 24236066, 2013). "Based on these findings, one might argue that TNF-α plays a key role in low-grade inflammation-induced β-cell dysfunction that precedes the overt insulin resistance in obese adults." (PMID 24454366, 2013). "WAE might alleviate insulin resistance in TNF-α-treated FL83B cells by activating PI3K-Akt/PKB signaling and inhibiting inflammatory response via suppression of JNK, rather than ERK, activation." (PMID 23389304, 2013). "TNF-α is reported to demonstrate wide range of effects in pathogenesis of insulin resistance." (PMID 23762871, 2013). "Interestingly, the inflammatory cytokines IL-1β, TNF-a, and IL-6 expression increased significantly and induced insulin resistance in the HFD-Nrf2-null group, compared with the HFD-WT group." (PMID 24188280, 2013). "Moreover, the progressive development of insulin resistance during pregnancy is due, in part, to placental cytokines such as TNF-α and leptin." (PMID 23805905, 2013). "The proinflammatory effects of resistin were attributed to its ability to activate NF-kB signaling pathway and subsequently increase the production of proinflammatory cytokines including TNF-α and IL-6, both of which can impair insulin signaling pathways and lead to insulin resistance." (PMID 23772224, 2013). "Furthermore, TNF-α has been shown to be a significant independent predictor of insulin resistance in GDM." (PMID 23691290, 2013). "We invoked chronic, low-grade inflammation by exposing C2C12 myotubes to a relatively low level of TNF-α for 4 days, as the biophysical effects of TNF-α and its downstream signaling network were well established by the induction of insulin resistance in various animal models." (PMID 24349514, 2013). "Elevated levels of TNF-α have been observed in obese and insulin resistance humans and animals." (PMID 23762871, 2013). "TNF-α induces nuclear transcription factor-κB (NF-κB) activation and leads to oxidative stress, which exacerbates pathological processes leading to glucose intolerance and insulin resistance." (PMID 23843781, 2013). "Exercise also confers protection against TNF-induced insulin resistance." (PMID 23691290, 2013). "Moller also suggests that downregulation of GLUT4 (among other metabolic components) may lead to better understanding of the mediation of TNFα in inducing insulin resistance." (PMID 24324517, 2013).
Insulin resistance (continued). "Given that TNFα activates proinflammatory signal cascades as well as inhibits insulin receptor signaling, this molecule is thought to be a major player linking adipose tissue inflammation and insulin resistance." (PMID 23964268, 2013). "3T3-L1 cells were treated with TNF-α for 4 days or Dex for 8 days to induce insulin resistance." (PMID 24367624, 2013). "TNF-α, secreted by adipose tissue, may play a critical role in insulin resistance and the pathogenesis of type 2 diabetes." (PMID 23762057, 2013). "We found little evidence of this on our selected population with no independent association of insulin resistance with either serum leptin or TNF-α." (PMID 23671875, 2013). "We investigated adiponectin, leptin, and TNF-α and assessed the contribution of these molecules to insulin resistance in south Asians.Hypothesis." (PMID 23671875, 2013). "Effect of fructose- induced insulin resistance (IR, 10% in drinking water, for 12 weeks) and daily oral administration of quercetin (50 mg.kg−1) on body weight, blood glucose, serum insulin, insulin resistance (IR) index, TNF-α, C-reactive protein (CRP), systolic BP." (PMID 23717483, 2013). "Elevated plasma TNF-α levels may play an important role in insulin resistance by impairing insulin signaling." (PMID 23437347, 2013). "However, the number of patients that fulfilled the inclusion criteria for this study (that is, insulin resistance, anti-TNFα naive and embarking on anti-TNFα) is limited." (PMID 22765047, 2012). "Also, TNF-α deteriorates insulin signaling and reduces glucose uptake, mediating the relationship of insulin resistance with manifestations of the metabolic syndrome (MS)." (PMID 23176569, 2012). "Additionally, the inflammatory kinase I-kappa-B kinase-β (Ikκβ) contributes to insulin resistance by activating NF-κB and induces production of various inflammatory cytokines, including TNF-α and IL-6." (PMID 23213270, 2012). "The authors also showed that the IL-10 produced by AAMφs had the ability to block the pathological effects of TNF-α in adipose tissue during insulin sensitivity, suggesting that while CAMφs have insulin resistance-inducing effects, AAMφs have a protector role within AT." (PMID 23326021, 2012). "Plasma leptin, nonesterified fatty acid, and tumor necrosis factor-α levels are all elevated in obese subjects and are thought to play essential roles in causing insulin resistance." (PMID 22851968, 2012). "Studies in mice showed a positive correlation between TNF-α quantity and insulin resistance." (PMID 22234148, 2012). "In analogy, elevated IL-1, IL-6, and TNF-α levels in septic patients may contribute to insulin resistance." (PMID 22272381, 2012). "It is therefore plausible that increased IL-6 expression in adipose tissue after envenomation may be due to TNF-α production, suggesting that TNF-α and IL-1β work in concert to cause insulin resistance." (PMID 22816003, 2012). "However, FTox-G50-induced insulin resistance on glucose metabolism was abolished by anti-TNF-α treatment, suggesting that insulin resistance induced by venom is TNF-α dependent." (PMID 22816003, 2012). "However, many researches affirm that the most important mediator related with obesity and insulin resistance is TNF-α, expressed plentifully in adipose tissue, in obese individuals with severe insulin resistance, and in neoplastic patients." (PMID 23009606, 2012). "As one of the most widely studied cytokines, TNF-α is reported to modulate insulin resistance." (PMID 22110480, 2012). "This site has been described as substrate for S6K1 and as part of TNF-α-induced insulin resistance." (PMID 22912850, 2012). "Pro-inflammatory cytokines: TNF-α, IL-6 and IL-1β are synthesized by numerous tissues, including obese adipose tissue, which, in addition to their well described pro-inflammatory properties, are involved in the genesis of insulin resistance." (PMID 23201837, 2012).